PTK2 (protein tyrosine kinase 2)
Diseases named in the same sentence as PTK2 in open-access papers (continued):
Sharing a sentence is not in itself a finding about the gene and the disease.
pancreatic NETs (2 papers, 2019 to 2025). "The clinical relevance of these findings is further underscored by our in silico analysis of publicly available transcriptomic datasets, which revealed that PTK2 is highly expressed in rectal and small intestinal NETs compared to pancreatic NETs." (PMID 40832091, 2025). "In silico analysis revealed elevated PTK2 expression in rectal and small intestinal NETs relative to pancreatic NETs." (PMID 40832091, 2025).
preeclampsia (2 papers, 2020 to 2021). Preeclampsia is a hypertensive disorder of pregnancy that is characterized by new-onset hypertension with proteinuria presenting after 20 weeks of gestation, and depending on mild or severe forms may initially present with severe headache, visual disturbances, and hyperreflexia. "Among these genes, LAMB2, PTK2, RAC1, QSOX1, FN1, and VCAM1 have known associations with the pathogenic mechanisms of preeclampsia." (PMID 35719905, 2021). "Protein tyrosine kinase 2 (PTK2) (focal adhesion kinase) is differentially expressed in preeclampsia and reported as among the promising biomarkers for preeclampsia." (PMID 35719905, 2021).
thymoma (2 papers, 2021 to 2025). A neoplasm arising from the epithelial cells of the thymus. "For example, PTK2 figured significantly in breast cancer (BRCA), three kidney cancer data sets [kidney chromophobe (KICH), kidney renal clear cell carcinoma (KIRC) and kidney renal papillary cell carcinoma (KIRP)], and thymoma (THYM), while PRKDC has distinct patterns in seven cancer studies." (PMID 34296749, 2021).
Ataxia (1 paper, 2022). Ataxia refers to impaired coordination of voluntary muscle movement. "Among the genes related to cerebellar volume in the four substructure GWASs we find genes related to ataxia (PEX7, MRPS27, PTK2), neurodevelopment (YPEL3, CASP6, TRIM11, GNB5) and microcephaly (PDCD6IP, USP28)." (PMID 35546225, 2022).
hyperlipidemia (1 paper, 2021). "Similarly, ESR1(ERα), MAOA, MGAM, PTK2, MMP1, GNB5, PIK3R3, and other targets had higher degree values, suggesting that these genes might be the core targets of PCE intervention in hyperlipidemia." (PMID 34925692, 2021).
intracerebral hemorrhage (1 paper, 2025). A cerebrovascular disorder characterized by bleeding into one or both cerebral hemispheres including the basal ganglia and the cerebral cortex. "Importantly, Astragaloside IV likely prevents the proliferation and migration of microglia/macrophages after intracerebral hemorrhage (ICH) by binding its transformed products to CDC42, PTK2, and CSF1R in C57 BL/6 mice model." (PMID 41049135, 2025).
myeloid malignancy (1 paper, 2021). "We show that these patients may benefit from therapy with inhibitors of focal adhesion kinase, encoded by PTK2, demonstrating additional utility of transcriptome-based testing for therapy selection in myeloid malignancy." (PMID 33931648, 2021).
periodontal disease (1 paper, 2023). "Four of them, IL1B (p = 0.023), IL1RN (p = 0.048), BGLAP (p = 0.0372) and PTK2 (p = 0.0075) were down-regulated in the periodontal disease and implant rejection group, and only one was overexpressed: FOXO1A (p = 0.0552)." (PMID 37175429, 2023).
plasma cell leukemia (1 paper, 2022). An aggressive plasma cell neoplasm characterized by the presence of neoplastic plasma cells in the peripheral blood. "It is interesting to note that two other MAPK pathway-enriched genes, SPTB and PTK2/FAK1, also play a role in the development of an aggressive and rare form of EMM called plasma cell leukemia." (PMID 36611892, 2022).
rectal NETs (1 paper, 2025). "PTK2 (FAK) expression was significantly higher in rectal NETs compared to pancreatic and small intestinal NETs." (PMID 40832091, 2025).
skin pigmentation disorder (1 paper, 2025). A pigmentation disease that involves the zone of skin. "In conclusion, our findings identified a critical melanophagy regulatory cascade – PTK2-ITCH-MLANA-OPTN that sheds light on melanosome degradation and suggests new treatments for skin pigmentation disorders." (PMID 39477686, 2025).
tumor (1,304 papers, 2003 to 2026). "Focal adhesion kinase (FAK) signalling was enhanced in ACC compared to normal adrenal glands, with PTK2 (encoding FAK) upregulated in 44% of tumour samples due to copy number alterations." (PMID 40650315, 2025). "Based on these observations, we suspect that when VEGF‐associated angiogenesis is inhibited by Foretinib, tumor cells will seek to activate angiogenesis by introducing this splicing variant of PTK2." (PMID 40323145, 2025). "In ACC, 44% (39/89) of tumours showed FAK encoding PTK2 gene amplification, leading to increased PTK2 expression compared to diploid ACCs (p < 0.0001) and those with shallow deletions (p < 0.0001)." (PMID 40650315, 2025). "Correlations between FAK/PTK2 and 2 immunotherapeutic biomarkers (tumor mutation load and microsatellite instability) were studied." (PMID 38518034, 2024). "This study was aimed to evaluate the expression of FAK/PTK2 in different cancer types; its prognostic value in different tumors; its relationship with tumor immune characteristics, and its association with drug response." (PMID 38518034, 2024). "Focal adhesion kinase (FAK) is a multifunctional tyrosine kinase protein encoded by PTK2 (or FAK) that is overexpressed in tumor cells associated with adverse clinical outcomes." (PMID 36407100, 2022). "Overexpression of IGF1R and PTK2 rescued the inhibition of tumor growth and metastasis caused by BACH1-depletion." (PMID 35154476, 2022). "Both elevated IGF1R and PTK2 expression were related to increased tumor number, tumor encapsulation loss, microvascular invasion, less differentiation, and poor TNM staging." (PMID 35154476, 2022). "Differently to other genes, only a low number of missense mutations of the PTK2 gene have been found in tumor lesions." (PMID 33562737, 2021). "Together, these observations suggest that higher expression of SMARCE1 and PTK2 increases risk of tumor relapse, and SMARCE1 likely plays a key role in regulating PTK2 expression in luminal B and basal-like tumors." (PMID 27495308, 2016). "PTK2 encodes protein focal adhesion kinease which regulates cell adhesion in extracellular matrix and promote tumor invasion in oral carcinogenesis." (PMID 23405089, 2013). "In two HCC patient cohorts (cohort I, n = 260; cohort II, n = 280), ETV1 expression was correlated with PTK2 and c-MET expression, and elevated expression of PTK2 or c-MET was associated with poor tumor differentiation, microvascular invasion, loss of encapsulation, and advanced TNM stage." (PMID 36109787, 2022). "Previous studies have shown that PTK2 overexpression may be associated with tumor cell migration and activation of the extracellular-signal-regulated kinase signaling pathway." (PMID 36533074, 2022). "Furthermore, amplification of the gene PTK2 is also observed in up to 20% of HCC, resulting in overexpression of its encoded protein focal adhesion kinase (FAK), which is an important driver of tumor proliferation and metastasis." (PMID 33807722, 2021). "Moreover, PTK2 deletions in mice are associated with the induction of cell death and the inhibition of tumor progression." (PMID 34439361, 2021). "Clinical studies showed that PTK2 is associated with tumor progression in various cancers." (PMID 31791326, 2019). "In addition, PTK2 overexpression is associated with poor prognosis in several tumor types." (PMID 36533074, 2022). "PTK2 functions as a biomarker and druggable target that integrates tumor growth, immune modulation, and metabolic adaptation." (PMID 41657774, 2026). "Separately, protein tyrosine kinase 2 (PTK2) promotes HCC tumor growth and sustains Liver-CSC characteristics by augmenting the Wnt/β-catenin pathway." (PMID 41438763, 2025).
tumor (continued). "To explore the clinical relevance of FAK (PTK2) expression in GI-NETs, we analyzed PTK2 gene levels across different tumor types and tissue origins using publicly available datasets (GSE98894)." (PMID 40832091, 2025). "Clinical parameters including patient age, gender, survival rate, and tumor stage were analyzed to evaluate the prognostic value of FAK/PTK2." (PMID 38518034, 2024). "Meanwhile, FAK/PTK2 expression is significantly correlated with tumor stage of some cancers, including BLCA, COAD, KIRC, KIRP, and TGCT." (PMID 38518034, 2024). "FAK/PTK2 activity is significantly increased in tumor groups of CHOL, COAD, HNSC, LIHC, LUAD, LUSC, and STAD, and is decreased in tumor groups of KIRC, KIRP, THCA, and UCEC." (PMID 38518034, 2024). "Most studies have found that PTK2 is often upregulated in solid epithelial cancers, where it contributes to tumor malignant behavior." (PMID 37875515, 2023). "In the protein level, the gene expression of HSP90AA1, NFKB2, PTK2 was upregulated in tumor tissues, and CLU, JAK2, MAP3K5, and S100B were downregulated in the normal tissues." (PMID 36323529, 2023). "Previous studies have revealed that the activation of PTK2 protects tumor cells via sustaining survival signaling." (PMID 38067143, 2023). "Positive TLR4 or PTK2 expression was accompanied by incomplete tumor encapsulation, microvascular invasion, poor differentiation, advanced TNM stage, poor OS, and high recurrence rates in our cohorts." (PMID 37554278, 2023). "Consistently, silencing IGF1R or PTK2 decreased tumor growth in the liver, the occurrence of pulmonary metastasis, and the number of pulmonary metastasis lesions, resulting in prolonged OS of nude mice bearing orthotopic xenografts of PLC/PRF/5-LV-BACH1 cells." (PMID 35154476, 2022). "PTK2 (protein tyrosine kinase 2), a cytoplasmic protein tyrosine kinase, was reported to favor tumor progression and overexpressed in several advanced-stage solid cancers." (PMID 35578198, 2022). "In contrast, two down-regulated genes in OVCAR-3 and OAW-42 cells, the USP12 and PTK2, reported to promote tumor cell growth, both exhibited a weak positive correlation with an adverse OS, (HR = 1.17, p = 0.018) and (HR = 1.18, p = 0.016), respectively." (PMID 36077645, 2022). "Overexpression of circ-PTK2 enhanced tumor formation and was correlated to expression of EMT pathway markers." (PMID 34034740, 2021). "In particular, monocytic MDSC subsets Gr1−/CD11b−, Gr1−/CD11b+ triggered an M2-dependent immune response, creating an immunosuppressive tumor-promoting network via circHIPK3/PTK2 enrichment." (PMID 34326381, 2021). "Similar to Sdc-1 mode of action, spliced F3 binds to the endothelial cell integrin αvβ3 and α6β1 to evoke tumor angiogenesis via protein tyrosine kinase-2 signaling." (PMID 34066023, 2021). "In the present study we characterize for the first time the role of circHIPK3/PTK2 in tumor macrophages-related immunosuppression." (PMID 34326381, 2021). "Specifically, monocytic MDSC subsets Gr1−/CD11b−, Gr1−/CD11b+ elicited an M2-dependent immune response, creating an immunosuppressive tumor-promoting network via circ HIPK3/PTK2 up regulation." (PMID 34326381, 2021). "In TCGA PanCancer Atlas, PTK2 (FAK) is overexpressed in approximately 25% of HNSCC tumors and FAK mRNA is significantly upregulated in tumor versus normal tissues, further highlighting a role for FAK in HNSCC." (PMID 34031486, 2021). "PTK2 inhibitors are able to decrease tumor growth, metastasis, and angiogenesis and thus can act as promising chemotherapeutics." (PMID 32964029, 2020). "With the exception of tumor 2, all tumor samples showed characteristic mutations of HNSCC including amplification of 3q26.2 (TP63, SOX2, PIK3CA), 5q14.3 (APC), 8q24.3 (PTK2), 8q22.3 (LRP12) as well as loss and/or LOH of 9p21.3 (CDKN2A)." (PMID 32426287, 2020).
tumor (continued). "As a cytoplasmic protein tyrosine kinase, PTK2 can enhance cell motility, survival, and proliferation through effects on cancer cells and stromal cells in the tumor microenvironment." (PMID 32964029, 2020). "Among these, the focal adhesion kinase (FAK, also known as PTK2), has been shown to exert a main role in facilitating and promoting the invasiveness of tumor cells." (PMID 30728047, 2019). "KCNMA1 exerts a tumor suppressive function by regulating the PTK2 expression to activate the PI3K-AKT pathway." (PMID 28231797, 2017). "PTK2 can enhance tumor progression and metastasis through effects on cancer cells, as well as stromal cells of the tumor microenvironment." (PMID 28231797, 2017). "Emerging evidence suggests that PTK2 plays a key role in protecting tumor cells against anoikis by sustaining survival signaling." (PMID 27495308, 2016). "In fact, the regulation of NFE2L2, and PTK2 expression are linked indirectly through FGF7, a member of the fibroblast growth factor family involved in wound repair and tumor development." (PMID 27812189, 2016). "Substantial evidence has shown that activated PTK2 leads to tumor growth and metastasis, and the level of expression is substantially linked to the invasive potential of tumors." (PMID 21211025, 2011). "PTK2 expression showed a positive correlation with mast cells, but was negatively associated with CD8+ T cells, macrophages, and NK cells, suggesting a potential role in immune suppression across both tumor stages." (PMID 40943183, 2025). "While PTK2 expression alone did not serve as a prognostic marker, tumours with high FAK activity were associated with worse progression-free, disease-specific, and overall survival." (PMID 40650315, 2025). "Moreover, genes regulating adhesion, ECM, Wnt signalling, and migration were differentially methylated in PTK2-high versus PTK2-low tumours." (PMID 40650315, 2025). "PTK2 showed strong positive correlations with activated T cells and M2 macrophages, and negative correlations with naïve and memory B cells, activated dendritic cells, eosinophils, and neutrophils across both tumor types." (PMID 40943183, 2025). "Notably, both FAK encoding genes PTK2 and ASAP1 are located in the oncogenomic locus 8q24 and are associated with tumor metastasis and recurrence." (PMID 38410129, 2024). "Both PI3K and PTK2 are involved in pathways integral to tumor initiation and progression." (PMID 38694917, 2024). "Although not all cancers show an association between tumor immune microenvironment and FAK/PTK2, these findings highlight the immune role of FAK/PTK2 in specific cancers, which will be used as an effective means to target them." (PMID 38518034, 2024). "PTK2, a non‐receptor tyrosine kinase, plays vital roles in diverse cellular processes, such as growth factors signaling, cell cycle, cell survival, angiogenesis, and immunosuppressive tumor microenvironments." (PMID 38545258, 2024). "PTK2 or FAK has been shown to assist in and stimulate tumor cell invasiveness." (PMID 38202644, 2023). "Previously, studies have shown that lncRNAs could influence the activation of the PTK2 pathway, thereby facilitating tumor advancement." (PMID 37875515, 2023). "In MYCN-amplified NB cells, after inhibiting the expression of PTK2 with two PTK2 small-molecule inhibitors, the proliferation of tumor cells was significantly reduced, the percentage of cells in the G1 phase was significantly increased, and that in the S phase was decreased." (PMID 36770809, 2023). "PTK2 facilitates tumor progression and metastasis via its kinase activity and scaffolding function." (PMID 35154476, 2022). "FAK (Focal adhesion kinase), encoded by the PTK2 (protein tyrosine kinase) gene is highly expressed in multiple cancers including OC, and is associated with tumor metastasis and chemoresistance." (PMID 35574330, 2022).
tumor (continued). "In addition, PTK2 was significantly correlated with the gene markers of B cells, T cells, CD8+ T cells, monocytes, tumor-associated macrophages (TAMs), M1 macrophages, M2 macrophages, neutrophils, natural killer (NK) cells, and dendritic cells." (PMID 36533074, 2022). "In addition, protein tyrosine kinase 2 (PTK2) has been reported as tumor-promoting factors in HCC with their abilities to upregulate Wet signaling by maintaining CSC properties in HCC." (PMID 36358885, 2022). "The survival of tumor-bearing mice was shortened via PTK2 and c-MET overexpression." (PMID 36109787, 2022). "On the other hand, Ingenuity pathway analysis software (IPA, Qiagen) identified three genes with notably decreased mRNA levels upon chemerin treatment, USP12, CAT and PTK2 (FAK), which exert tumor-promoting effects and stimulate proliferation of cancer cell lines in vitro." (PMID 36077645, 2022). "Furthermore, a significant increase in PTK2 expression was observed in paired tumor samples compared with adjacent normal samples." (PMID 36533074, 2022). "These lines of evidence suggest that PTK2 has a crucial role in tumor occurrence and development." (PMID 36533074, 2022). "Interestingly, both PTK2 and ASAP1 are located in an oncogenic genomic locus 8q24 and are associated with tumor metastasis and recurrence." (PMID 35574330, 2022). "According to our experiment and previous studies, we speculate that GL-pp might inhibit tumor metastasis by disturbing the function of FAK and the pathway involving Ptk2 and Grb2." (PMID 34305583, 2021). "PTK2 silencing, on the other hand, led to increase in apoptosis and a decrease in tumor growth." (PMID 33589614, 2021). "We used a tumor formation assay to investigate the functions of circ-PTK2 in vivo." (PMID 34034740, 2021). "The persistence of clonal mutations in ATM, PTK2, GLI3 and CLTCL1 in all tumour locations analysed in samples from diagnosis and at relapse in patient CB1002 could indicate the relevance of these SNVs for tumour progression." (PMID 34815394, 2021). "Substantial evidence has shown that activated PTK2 expression level links to tumor progression." (PMID 33679866, 2020). "Tumor cells that detach from the ECM can escape from anoikis via PTK2 activation." (PMID 29338725, 2018). "Spliced TF may stimulate tumor angiogenesis through protein tyrosine kinase-2 signaling by ligating to endothelial cell integrins such as αvβ3 and α6β1." (PMID 29017512, 2017). "The presence of PTK2 gene amplification was confirmed by CGH performed on 19 surgically resected HCCs, revealing that this mutation was detected in 26% of cases and exclusively in moderately-differentiated and poorly-differentiated tumours." (PMID 28067792, 2017). "In particular, we observed that both HPV-positive and -negative OPSCC tumours had elevated levels of Src and PTK2 (encodes focal adhesion kinase (FAK)) genes, which were associated with p63 binding sites detected by ChIP-seq in normal cells." (PMID 26001294, 2017). "Furthermore, the anti-tumor effect of KCNMA1was mediated through suppressing the expression of PTK2." (PMID 28231797, 2017). "Interestingly, we observed EGF-induced alternative promoter usage of genes that have previously been implicated in tumor progression (e.g., VEGFC, PTK2, IL18 and VAV3) or in cell survival/proliferation (e.g., FBXW7, BID, ABL2)." (PMID 24324612, 2013). "Importantly, PTK2 expression positively correlated with RB1 levels across all tumor types, suggesting a consistent transcriptional relationship that may reflect a broader, tissue-independent mechanism of regulation." (PMID 40832091, 2025). "Therefore, PTK2 is an important driver molecule in tumor angiogenesis, and targeting PTK2 may be a promising therapeutic strategy for cancer." (PMID 36158681, 2022).